IL10 (interleukin 10)
Diseases named in the same sentence as IL10 in open-access papers (continued):
Sharing a sentence is not in itself a finding about the gene and the disease.
lung carcinoma (continued). "Laricitrin decreases the lung cancer-mediated activation of STAT3, subsequently reducing IL-10 levels in DCs." (PMID 27833081, 2016). "This study investigates how lung cancer increases the activation and DNA binding activity of STAT3, which in turn enhances the expression of IL-10 in DCs." (PMID 27833081, 2016). "To examine the molecular mechanism of IL10 in lung cancer formation, we studied IL10 expression in Kras4bG12D- and EGFRL858R-induced lung cancer mice." (PMID 26956044, 2016). "The result shows that lung cancer A549 and CL1-5 cells stimulated DCs to express a large amount of IL-10." (PMID 27833081, 2016). "Human lung cancer A549 and CL1-5 cells change the phenotype of DCs that express to high levels of IL-10 and prime T cells towards an immune suppression type-2 response (Th2)." (PMID 27833081, 2016). "For lung cancer, high intra-tumoral concentrations of CXCR2 ligands (CXCL1, CXCL5, and CXCL8) and type 2 cytokines IL-4, IL-5, IL-10, and IL-13 have been reported for non-small cell lung cancer." (PMID 26231039, 2015). "AMs in lung cancer have been shown to exert protumour effects via their secretion of anti-inflammatory/immunosuppressive cytokines such as TGF-β and IL-10." (PMID 26316944, 2014). "We investigated the correlation between plasma pro-inflammatory cytokines (including plasma RANTES, IL-10, and IL-8) levels and clinical outcomes following EGFR-TKI treatment in lung cancer patients." (PMID 23566546, 2013). "Additionally, TAMs and MDSCs suppress NK cell function by releasing IL-10 and TGF-β, correlating with lower survival rates in lung cancer patients." (PMID 40136652, 2025). "Although most evidence comes from murine studies, human lung cancer patients show higher levels of CD24+IL-10+ B cells than normal lung tissue." (PMID 40136652, 2025). "Here, we explored the anti-tumor effect of CAP based on a co-culture model of macrophages and lung cancer cells, and it was found that CAP could induce M2 polarization of macrophages and then release IL-10." (PMID 41145470, 2025). "In lung cancer, cancer cells can secrete TGF‐β and IL‐10 to induce naïve T cells to differentiate into Tregs, and tumour antigens presented by APCs further enhance Treg activation and accumulation in the tumour microenvironment, where Tregs inhibit NK cell‐mediated cytotoxicity." (PMID 41200753, 2025). "We examined eight key cytokines (Interleukin-1, IL-6, IL-8, IL-10, IL-12p70, monocyte chemotactic protein-1 (MCP-1), interferon-gamma (IFN-γ), and tumor necrosis factor-alpha (TNF-α)) in the plasma of 104 lung cancer patients and 48 cancer-free individuals using the FirePlex Immunoassay." (PMID 38276239, 2024). "This is in keeping with data from EGFR-mutated lung cancer where there is overproduction of negative immune modulators such as TGF-β and IL-10, directly suppressing NK, dendritic and cytotoxic T-cell function." (PMID 39395265, 2024). "Furthermore, in the plasma samples of AA participants, IL-10 and MCP-1 exhibited a notable increase in lung cancer patients compared to cancer-free African American controls (p < 0.0001)." (PMID 38276239, 2024). "IL-10 and MCP-1 exhibit notably elevated levels in the plasma of AA lung cancer patients." (PMID 38276239, 2024). "In addition, IL-10 expression was increased in plasma samples or TCGA datasets from patients with GBM and lung cancer." (PMID 38521953, 2024). "In addition, we detected the levels of Th17-related cytokine (IL-17) and Treg-related cytokines (IL-10, TGF-β) in the peripheral blood of elderly lung cancer patients after operation, and found consistent tendency with Th17 and Treg cells." (PMID 36434505, 2022). "Lung cancer cells have been shown to produce a variety of immunosuppressive molecules including TGF-beta, prostaglandin E2, IL-10, and cyclooxygenase-2 that can affect dendritic cell processing and presentation, as well as the effector functions of cytotoxic T lymphocytes." (PMID 35632496, 2022).
lung carcinoma (continued). "In addition, endurance exercise can reduce the proportion of M1-type TAMs in lung cancer tissues, while HIIT antagonistically regulates M1 and M2 polarization of TAMs by increasing the levels of IL-10 and IL-12 in lung cancer tissues and circulating IFN-γ." (PMID 36186906, 2022). "The percentage of CD137+ regulatory T cells (Tregs) in the blood of lung cancer patients was also increased, and further enriched at the tumor site; Foxp3, CTLA-4, IL-10, IL-35-Ebi3, sCD137 and costimulatory molecules expression were also higher, indicating increased immunosuppressive activity." (PMID 35197968, 2022). "For example, identified immunostimulatory factors (e.g. IFNG in lung cancer) are associated with a negative prognosis, whereas immunosuppressive factors (e.g. FOXP3/IL10 in ovarian cancer) are associated with a positive prognosis." (PMID 36419893, 2022). "Overall, HIIT combined with targeting IL-10, CD47 and CD24 could be a novel strategy for the treatment of lung cancer." (PMID 36186906, 2022). "The most known cytokines to induce T cell dysfunction are IL-10, IL-6 and TNF-α, while TGF-β role in cancer is mostly related to epithelial-to-mesenchymal transition (EMT), invasion and metastasis in melanoma, breast and lung cancer." (PMID 33466674, 2021). "Treg cells could inhibit the activation of T lymphocytes by secreting cytokines such as IL-4, IL-10, and TGF-β, which regulate the immune function of tumor patients and promote the proliferation of lung cancer cells." (PMID 33879165, 2021). "EV-miR-103a from hypoxic lung cancer cells enhances M2 macrophage polarization by targeting PTEN, which further promotes the migration and invasion of lung cancer cells and tube formation of HUVECs by secreting IL-10, CCL18 and VEGF- A." (PMID 32503543, 2020). "Future investigation will show whether IL-10 is involved in the high PD-L1/CD274 expression of monocytes and blood DC subtypes observed in lung cancer patients with a poor therapy response to anti-PD1 therapies." (PMID 33066260, 2020). "USP17 could be induced by cytokines secreted from macrophages because various cytokines, including TNF-α, IL-1β, IL-4, IL-6, IL-8, IL-10, CXCL12, CCL18, and CCL22, were able to induce USP17 expression in H1299 and D121 lung cancer cells." (PMID 30038267, 2018). "In lung cancer cells, LPS-triggered TLR4 activation enhances the secretion of IL-10." (PMID 28881826, 2017). "Although IL-10 concentration has been previously shown to be increased in liver and lung cancers, there is no documentation of increased IL-10 concentrations in GBC and cholangiocellular carcinoma." (PMID 29410961, 2017). "Similarly, PBMCs from smokers, a population well known to be at high risk of lung cancer, released higher levels of IL-1α and IL-10 than PBMCs from non-smokers, implying that the release of both types of cytokines may favour cell transformation and thus carcinogenesis." (PMID 28223692, 2017). "Previously our study showed that lung cancer cells impair the differentiation and function of DCs, which is supported by changing phenotype (decreasing CD1a up-regulation and the appearance of CD14) and expression of high levels of IL-10." (PMID 27833081, 2016). "Therefore, IL-10 expression and CD1a/CD14 ratio are critical indicators for assessing the degrees of differentiation and function of DCs in lung cancer." (PMID 27833081, 2016). "Although the in vivo role of IL10 in lung cancer has not been previously elucidated, in this study, we showed that IL10 was highly increased in lung cancer, and EGF promoted proliferation by increasing IL10 secretion." (PMID 26956044, 2016). "IL10 and EGFR co-regulation produces a vicious cycle for lung cancer development." (PMID 26956044, 2016). "Finally, because IL10 deprivation abolishes lung cancer formation by inhibiting the formation of the microenvironment and the expression of EGFR, the future development of anti-IL10 compound(s) will be of benefit to lung cancer therapy." (PMID 26956044, 2016).
lung carcinoma (continued). "In conclusion, IL10 appears to have a positive effect on the formation of the tumor microenvironment via M2 macrophages as well as through the expression of EGFR in cancer cells, thereby enhancing lung cancer formation." (PMID 26956044, 2016). "In addition, IL-10 decreased golgi apparatus (GA) and rough endoplasmic reticulum (RER) function in AMs from patients with lung cancer." (PMID 26316944, 2014). "As IL-10 and TGF-beta expressing T cells are known to play a crucial role for inducing Foxp3+ T regulatory cells and controlling immune responses in NSCLC, these results suggest that IL-9 plays an important role in regulating immune responses in lung cancer in vivo." (PMID 35514957, 2022). "Therefore, in this review, we summarized the published literature from the year 2000 to the year 2019, specifically focusing on the role of IL6, TNFα, IL10, CCL2, CX3CL1, IL8 in the macrophages-tumor cells crosstalk; leading to lung cancer development and progression." (PMID 32219066, 2020). "Interestingly, we also observed that lung cancer cells promoted M2 polarization in macrophages as indicated by changes in levels of the M1-macrophage markers TNF-α and IL-12 and the M2-macrophage markers IL-10 and TGF-β." (PMID 29245941, 2017). "However, the transfer of iDC or DC-based HHP lung cancer vaccine into serum containing medium did not induce IL-12p70 or IL-10 production." (PMID 28187172, 2017). "Furthermore, among the 60 lung cancer patients, the average concentration of IL10 was obviously higher in stages III & IV than in stages I & II, implying an involvement of IL10 in tumor progression." (PMID 26956044, 2016). "Moreover, both IL10 and EGFR enhance lung cancer formation, and IL10 might increase EGFR expression." (PMID 26956044, 2016). "We found that IL10 was increased in Kras4bG12D- and EGFRL858R-induced lung cancer mice, which is consistent with the results in lung cancer patients and indicates that Kras and EGFR activation are involved in IL10 expression and might be positively related to lung cancer formation." (PMID 26956044, 2016). "Collectively, PBMCs from non-ATA carriers had lower apoptotic effects on lung cancer cells than did PBMCs from ATA carriers, and IL-10 was responsible for tumor cell apoptosis after co-culture with PBMCs." (PMID 22848356, 2012). "Analysis of the histological staining and nodule numbers showed that these IL10 knockout mice failed to develop significant lung tumors; thus, these data on Kras4bG12D- and EGFRL858R-induced lung cancer provide direct evidence that IL10 knockout inhibits lung cancer formation." (PMID 26956044, 2016).
psoriasis (185 papers, 2006 to 2026). An autoimmune condition characterized by red, well-delineated plaques with silvery scales that are usually on the extensor surfaces and scalp. "A deficiency in IL‐10 levels within the skin and serum of psoriasis patients plays a critical role in the pathogenesis of the disease." (PMID 41137524, 2026). "IL-10 deregulation has been implicated in the development of psoriasis, systemic lupus erythematosus, and allergies." (PMID 40572779, 2025). "The therapeutic response of IL-10 in psoriasis is associated with suppression of cutaneous inflammation, downregulation of the IL-8/CXCR2 pathway, and normalization of keratinocyte maturation." (PMID 38444844, 2024). "A number of IL10+ Breg cells was found to be inversely correlated with psoriasis severity and the number of pathogenic IL17A+CD3+ and IFNγ+CD3+ T cells." (PMID 38203754, 2024). "Previous studies have shown that imiquimod-induced psoriasis-like skin inflammation in IL10-deficient mice was more severe and persistent than in wild-type mice." (PMID 38203754, 2024). "In contrast, as shown by our and other groups, IL-10 neutralization or IL-10 deficiency induced persistent psoriasis-like inflammation after IMQ application." (PMID 34616394, 2021). "Our findings indicate a relative deficiency in cutaneous IL-10 mRNA expression in both study groups, but that levels were significantly lower in patients with psoriasis." (PMID 34945130, 2021). "First, we studied circulating T cells producing the psoriasis hallmark cytokine IL-17A alongside IL-10 producing T regulatory (Treg) in psoriasis patients and HV." (PMID 34362923, 2021). "Some authors describe a deficiency in the expression of IL-10 mRNA in psoriasis in comparison to normal skin tissue." (PMID 32382290, 2020). "We show here that TLR2 deficiency unexpectedly exacerbates psoriasis-like skin inflammation through a decrease in regulatory T cells (Tregs) and impaired IL-10 production by Tregs and DCs." (PMID 33202847, 2020). "Two studies evaluated the association of the IL‐10 SNP rs1800872 with psoriasis risk using data on allelotype." (PMID 30523673, 2019). "A previous meta‐analysis by Lee, Choi, Ji, and Song, (2012 assessed the IL‐10 SNPs and psoriasis risk in 2012." (PMID 30523673, 2019). "Deficiency of anti-inflammatory cytokines IL-10 and IL-35 in patients with psoriasis are essential factor in pathogenesis." (PMID 31670376, 2019). "Current published studies fail to support an association of the IL‐1RN VNTR polymorphism and IL‐10 SNPs rs1800896, rs3021097, and rs1800872 with psoriasis risk." (PMID 30523673, 2019). "Our study seeks to systematically review the literature and meta‐analyze the results of case–control studies on the relation of IL‐1RN and IL‐10 polymorphisms with psoriasis risk." (PMID 30523673, 2019). "Some authors suggest that there is a mild deficiency in the expression of IL-10 messenger RNA in psoriasis in comparison with other inflammatory skin diseases." (PMID 31101850, 2019). "The IL-10 cytokine shows the opposite effect to IL-22, as the SNP observed in the vicinity of the IL-10 gene shows a clear genomic association with psoriasis." (PMID 21152006, 2010). "For example, polymorphisms of the INF-γ and IL-10 genes were shown to be associated with different levels of cytokine production in patients with psoriasis." (PMID 21152006, 2010). "In psoriasis, a common cutaneous immune disease, a relative deficiency in cutaneous IL-10 expression is observed." (PMID 20101303, 2009). "Especially, the excessive production of IL-10, which may aid in rebuilding and restoring the epidermal obstacles, are frequently compromised in psoriasis, in conjunction with inhibiting cytokines that cause inflammation." (PMID 40667480, 2025).
psoriasis (continued). "A mouse model study assessing the function of TLR2s in psoriasis pathogenesis surprisingly found that a deficiency in TLR2s actually caused more psoriasis-like skin inflammation and downregulated the protective anti-inflammatory agents IL-10 and regulatory T cells (Tregs)." (PMID 39337637, 2024). "Moreover, an IMQ-induced psoriasis model using IL-10 deficient (IL-10−/−) mice instead of wild-type (WT) mice, is characterized by the development of severe and persistent psoriatic inflammation." (PMID 37717073, 2023). "Additionally, the rs1800872 SNP in the IL10 gene, featuring the G allele, was associated with an elevated risk of psoriasis by downregulating the production of IL10, an anti-inflammatory cytokine involved in immune regulation." (PMID 37569685, 2023). "STAT3 participates in signaling downstream of multiple cytokines implicated in psoriasis, such as IL-6, IL-10, IL-20, IL-22, and IL-23, and may have a role in mediating the innate immune response in psoriatic epidermis." (PMID 32752186, 2020). "Moreover, the imbalance between Th1 and Th2 cells in psoriasis was confirmed by studies that showed interleukin-10 (IL-10) deficiency in psoriatic skin lesions." (PMID 32164227, 2020). "The present study carried out a meta‐analysis to investigate whether the interleukin‐1 receptor antagonist (IL‐1RN) VNTR polymorphism and three IL‐10 single‐nucleotide polymorphisms (SNPs) rs1800896, rs3021097, and rs1800872 are associated with psoriasis risk." (PMID 30523673, 2019). "Because IL‐1ra and IL‐10 play an important role in controlling inflammation, it is possible that genetic variants in the IL‐1RN and IL‐10 genes may contribute to psoriasis susceptibility." (PMID 30523673, 2019). "In conclusion, current published studies fail to support the hypothesis that the IL‐1RN VNTR polymorphism and three common IL‐10 SNPs rs1800896, rs3021097, and rs1800872 are associated with psoriasis risk." (PMID 30523673, 2019). "Various psoriasis treatments have been associated with an increase in the levels of IL-10." (PMID 30744173, 2019). "Two studies investigated the relation between the IL‐10 SNP rs3021097 and psoriasis risk." (PMID 30523673, 2019). "Moreover, there are recent studies that link psoriasis onset with mutations in the promoter region of the IL-10 gene." (PMID 30744173, 2019). "IL-10 therapy has been proven to be clinically effective in the treatment of psoriasis by improving keratinocyte-associated pathologic parameters, and in the treatment of psoriatic arthritis by affecting endothelial activation, leukocyte recruitment, and effector function." (PMID 27903619, 2017). "In psoriasis an association with three variants of the IL-13 gene was observed: rs1800925, rs20541, and rs848 (This cytokine, such as IL-4 and IL-10, is secreted by Th2 lymphocytes and seems to be important in the innate and adaptive immune response dysregulation that leads to psoriasis)." (PMID 23971052, 2013). "Across all conditions, migration of inserted T cells towards the epidermis and the secretion of psoriasis-associated cytokines (IFN-γ, IL-17, TNF-α, IL-1β, CCL20, IL-6, and IL-10) was observed." (PMID 42039187, 2026). "The development of psoriasis involves numerous inflammation-related genes, including TNF (encoding tumor necrosis factor), CD4 (encoding the CD4 molecule), IL-10 (encoding Interleukin-10), and IL-4 (encoding Interleukin-4)." (PMID 40678620, 2025). "These markers, particularly CD163, are critical for monitoring macrophage polarization and inflammation in autoimmune conditions like psoriasis, and produce anti‐inflammatory cytokines such as IL‐10, TGF‐β." (PMID 40539722, 2025). "For example, polysaccharides from medicinal mushrooms like Ganoderma lucidum can modulate the immune function, increasing IL-10 and/or IL-1Ra expression, thus potentially reducing the autoimmune response that drives psoriasis." (PMID 39199158, 2024).